TNF (tumor necrosis factor)
Diseases named in the same sentence as TNF in open-access papers (continued):
Sharing a sentence is not in itself a finding about the gene and the disease.
ulcerative colitis (continued). "Generally, immunosuppressants and/or anti-TNF-α antibodies are commonly used to treat patients with ulcerative colitis." (PMID 35740465, 2022). "As a pro-inflammatory cytokine, TNF-α and IL-6 play important roles in the pathogenesis of ulcerative colitis." (PMID 36171753, 2022). "Our findings provide new insight into ulcerative colitis and provide evidence that pro-inflammatory mediators such as TNF-α enhance sensory neuron excitability of primary afferent fibers innervating the colon through modulation of P2X3 receptors activity." (PMID 36032155, 2022). "Here the authors design a therapy for ulcerative colitis based on a multitargeted genetic circuit to simultaneously target TNF-α, B7-1 and integrin α4, and show the therapy is effective in male mice with induced or spontaneous genetic colitis." (PMID 36171212, 2022). "A total of 4 literatures measured the improvement of ulcerative colitis by the levels of inflammatory factors (IL-6, TNF-α, and CRP)." (PMID 35912148, 2022). "The clinical value of existing therapeutic strategies of ulcerative colitis, including glucocorticoids, anti-tumor necrosis factor α (TNF-α), mesalamine, and thiopurines is still limited." (PMID 34489707, 2021). "The typical feature of ulcerative colitis was the inflammation of the intestinal mucosa, which resulted from the activation of the immune response by pro-inflammatory mediators (IL-6 and TNF-α) and anti-inflammatory cytokine IL-10." (PMID 35010176, 2021). "IFN-γ, TNF-α and other agents have been used to precondition MSCs to improve their therapeutic efficacy on ulcerative colitis." (PMID 34604183, 2021). "In a mice model of ulcerative colitis, polydatin targets the NF-κB-p65 pathway and exerts an anti-inflammatory effect by blocking the expression of the main inflammatory cytokines TNF-α, IL-6, and IL-1β." (PMID 34887932, 2021). "Due to ulcerative colitis, this patient received immunosuppressive treatment with a combination of infliximab—a mAb directed against TNF-α–together with azathioprine and prednisolone." (PMID 33613439, 2021). "At the same time, she had acute severe ulcerative colitis, so we started anti-tumor necrosis factor therapy despite serological tests and the recommendation to delay biological therapy administration for two-weeks." (PMID 34981697, 2021). "In our in vitro model, VD restored, at least in part, the expression and normal distribution of the TJ proteins, as reported in TNF-α-stimulated Caco-2 cells and in T84 cells or in colonic biopsies from patients with ulcerative colitis." (PMID 34445577, 2021). "Resistance to anti-TNF therapy in subgroups of ulcerative colitis (UC) patients is a major challenge and incurs significant treatment costs." (PMID 36700114, 2021). "TNF-α, IL-1β and IL-6 are the cytokines which play pro-inflammatory roles in the process of ulcerative colitis." (PMID 34604183, 2021). "Specifically, DHA has been shown to increase Cldn-1 expression in a mouse model of ulcerative colitis, in the intestinal cells of LPS-challenged piglets, and in TNF-alpha-challenged porcine epithelial cells." (PMID 34884896, 2021). "In clinical studies on treatments for ulcerative colitis and gastric ulcers, Gancao Xiexin decoction was proved to adjust the level of serum inflammatory factors including TNF-α, IFN-γ, IL-8, IL-12, IL-17, and IL-23." (PMID 34335839, 2021). "Ustekinumab linear clearance was in range of reported clearance values in other studies in IBD, and the TMDD PK model is consistent with the recent findings of the TNF-mediated PK of infliximab in ulcerative colitis." (PMID 34683880, 2021). "The DI requirement rate was higher both in those with prior anti-TNF exposure (p = 0.01) and with ulcerative colitis (p = 0.02)." (PMID 34069295, 2021).
ulcerative colitis (continued). "KEGG enrichment analysis also showed that these targets are mainly enriched in pathways related to inflammation, immunity, and tumors, such as JAK/STAT3, NF-κB, and TNF signaling pathways, which are related to the development of ulcerative colitis." (PMID 34211579, 2021). "Based on these results, both the FDA and EMA have released a warning, and the FDA has limited the use of tofacitinib to patients with ulcerative colitis that are refractory or intolerant to treatment with anti-TNF agents." (PMID 34453143, 2021). "It suggested that the free polyphenol extract of cherry likely acted as the inhibitor of IL-6 and TNF-α but the promotor of IL-10, and thus contributed to relieve ulcerative colitis induced by DSS in a cytokine-specific manner." (PMID 35010176, 2021). "Gallic acid, a major chemical component of QLX, was reported to inhibit NF‐κB expression and activation followed by down‐regulation of IL‐1, ILI‐6, IL‐12, IL‐17 and IL‐23, TGF‐β and TNF‐α expression in ulcerative colitis." (PMID 33982874, 2021). "In the clinical study, they found that patients with ulcerative colitis exhibit a significant upregulation of mRNA for ghrelin and tumor necrosis factor-α (TNF-α) in colonic mucosa in comparison to healthy controls." (PMID 34638910, 2021). "The secretion of several proinflammatory cytokines (INF-γ, IL-17, and TNF-α) was reduced by blockage of Kv1.3 and KCa3.1 in T-lymphocytes from patients with ulcerative colitis." (PMID 34639190, 2021). "Both AAs cause a reduction of interleukin 6, 8 and TNFα levels, and their serum levels appear to be decreased in human with IBD and ulcerative colitis." (PMID 32321505, 2020). "In the model mice of ulcerative colitis, the expression of TNF-α was increased; conversely the level of caspase 8 was decreased in the inflamed colonic epithelium (p < 0.05 vs. normal mice)." (PMID 33041798, 2020). "In trials of acute inflammation, such as steroid-refractory and severe ulcerative colitis (UC), anti-TNF agents were shown to have a favorable adverse event profile, in addition to inducing higher remission rates and improving the percentage of colon-salvage." (PMID 33426360, 2020). "The inflammatory cytokines, including TNF-α, IL-1β and IL-6, were also suppressed and the percentages of macrophages were decreased, after using a kind of anti-ulcerative colitis medicine in CAC." (PMID 33201893, 2020). "Given that sustained remission is the ultimate treatment goal in the management of patients with ulcerative colitis (UC), the decision to stop anti-tumor necrosis factor (anti-TNF) treatment in UC patients is difficult." (PMID 33154436, 2020). "EA was effective in regulating the levels of TNFα in animal models of ulcerative colitis and zymosan-induced acute arthritis." (PMID 32982761, 2020). "A recent study aimed at determining genetic factors associated with poor response to anti-TNF therapy, found that a strong association between a CD74 polymorphism and anti-TNF failure in patients with ulcerative colitis." (PMID 32655566, 2020). "Clinical studies have reported that a higher expression of TNF-α was detected in serum and colonic mucosa in ulcerative colitis (UC) patients." (PMID 33396265, 2020). "Although IL11 is upregulated in systemic sclerosis, TNF-resistant ulcerative colitis and asthma and despite SMCs being a source of IL11, the effect of IL11 function in SMC biology has not been studied." (PMID 31917819, 2020). "Oat beta-glucan has also been previously shown to decrease the mRNA and protein expression of pro-inflammatory cytokines such as IL-1β, IL-6, and TNF-α in mice suffering from dextran sulfate sodium (DSS)-induced ulcerative colitis." (PMID 32707913, 2020). "p38 is an important protein in ulcerative colitis, which can be activated by a variety of cytokines, such as hormones, IL-1, and TNF-α." (PMID 31139644, 2019).
ulcerative colitis (continued). "It is well known that ulcerative colitis is characterized by the production of a wide range of inflammatory cytokines, including TNF-α, IL-1β, and IL-6." (PMID 31827675, 2019). "Previous studies have demonstrated that TNF-α increases in ulcerative colitis (UC) patients, but the relationship between TNF-α and NOTCH signaling pathway in UC etiopathology needs further study." (PMID 32099606, 2019). "Another recent study in ulcerative colitis patients treated by anti-TNF therapy revealed lower dysbiosis indices and higher abundance of Faecalibacterium prausnitzii in responders compared with non-responders at baseline." (PMID 29615661, 2018). "TNF-α is an important constituent in the pathophysiology of ulcerative colitis, and thus, agents targeting TNF-α have been studied for ulcerative colitis." (PMID 29694505, 2018). "Adalimumab is a recombinant monoclonal antibody to tumor necrosis factor alpha (TNFα) used in the treatment of inflammatory and autoimmune conditions, including ulcerative colitis (UC)." (PMID 30648028, 2018). "Since DSS induced ulcerative colitis, the expressions of three proinflammatory cytokines (TNF-α, IL-6, and IL-1β) were examined in the serum and colorectum tissue." (PMID 29483924, 2018). "Antitumor necrosis factor alpha (anti-TNF alpha) agents such as infliximab are drugs that have been used for the treatment of ulcerative colitis for decades." (PMID 30533230, 2018). "In a mouse model of ulcerative colitis, which was induced by dextran sulfate sodium, expressions of TNF-α, IL-1β, and IL-6 were markedly up-regulated in the colon, resulting in intestinal mucosal inflammation." (PMID 29694505, 2018). "Loss of T-bet in the innate immune system leads to a transmissible form of ulcerative colitis in the TRUC (T-bet and Rag deficient Ulcerative Colitis) model, driven by transcriptional derepression of TNF in colonic mononuclear phagocytes." (PMID 28187197, 2017). "The Toronto consensus in 2015 recommends anti-TNF therapy to induce and maintain complete steroid-free remission in patients with steroid-dependent ulcerative colitis." (PMID 28069051, 2017). "There have been few reports on 2 tumor necrosis factor alpha inhibitors, infliximab and adalimumab, with respect to patient preference and efficacy in ulcerative colitis (UC)." (PMID 28796080, 2017). "The TLR5 N592S mutation also reportedly affects TNF-a and IFN-r levels in ulcerative colitis patients." (PMID 29179462, 2017). "Inhibition of tumor necrosis factor alpha (TNF-α) is very important for the control of inflammatory lesions in ulcerative colitis (UC)." (PMID 28796080, 2017). "It is well known that the TNF-α plays a central role in IBD pathology and anti-TNF-α therapy has been shown to be efficacious in the treatment of ulcerative colitis and Crohn’s disease." (PMID 27188220, 2016). "TNFα is a proinflammatory cytokine found at increased concentrations in the blood, colonic tissue and stools of ulcerative colitis patients." (PMID 27494322, 2016). "The treatment of ulcerative colitis (UC) patients with moderate to severe inflammatory activity with anti-tumor necrosis factor alpha (TNFα) antibodies leads to a clinical remission rate of 10% after 8 weeks of therapy." (PMID 27352964, 2016). "Upon admission to hospital for a major flare of her ulcerative colitis a clinical decision was made to initiate an anti-TNFα biological agent." (PMID 27169677, 2016). "For example, patients with ulcerative colitis who were treated with an anti-TNF-α agent were prone to infection with Listeria monocytogenes, a bacterium that mainly affects immunocompromised hosts." (PMID 25329064, 2014). "The results are in accordance with an earlier study where Lactobacillus delbrueckii and Lactobacillus fermentum ameliorated the inflammation by decreasing concentration of IL-6 and expression of TNF-α and NF-κB p65 in ulcerative colitis." (PMID 24966470, 2014).
ulcerative colitis (continued). "Activated macrophages and neutrophils secrete proinflammatory cytokines such as TNF-α, IL-1β, and IL-6 to regulate the inflammatory response in the colonic mucosa of patients with ulcerative colitis." (PMID 24971344, 2014). "Analysis was performed on randomized controlled trials that assessed anti-TNF-α therapy on ulcerative colitis patients that had previously failed therapy with corticosteroids and/or immunosuppressants." (PMID 24475168, 2014). "The proinflammatory cytokines TNFα and IL-6 play a crucial role in IBD and treatment with TNFα-blockers is a standard therapy for ulcerative colitis." (PMID 24120915, 2014). "Currently available drugs for the treatment of ulcerative colitis (UC) include salicylates, thiopurines, corticosteroids and new anti-tumour necrosis factor (TNF)-α biologics." (PMID 23961883, 2013). "For example, Liu and Wang showed that the serum levels of tumor necrosis factor-α (TNF-α) and interleukin-13 were significantly higher in rats with ulcerative colitis complicated with Shi-Re ZHENG, as compared with those without Shi-Re." (PMID 22829858, 2012). "TNF-α is also thought to be an important agent in the colonic inflammation of patients with ulcerative colitis (UC)." (PMID 19594939, 2009). "Genes up-regulated by C. jejuni that have been associated with active ulcerative colitis/IBD include chemokines, such as IL8 and CCL20 (macrophage inflammatory protein 3α) cytokines, including TNFα, eicosanoids and elafin." (PMID 19193236, 2009). "Fibroblasts from patients with ulcerative colitis also increased MMP-1 while treatment with imipramine resulted in MMP-1-levels with significant inhibition when compared to cells with IL-1β or TNF only." (PMID 19787068, 2009). "Neutrophil extracellular traps (NET) play a pivotal role in the pathogenesis of ulcerative colitis (UC) and may contribute to the impaired response to anti-tumor necrosis factor alpha (TNF-α) therapies." (PMID 40963602, 2025). "Both the innate and adaptive immune systems are implicated in IBD pathogenesis, with CD being associated with Th1/Th17 responses, producing cytokines like IL-17, IFN-γ, and TNF-α, whereas ulcerative colitis features a Th2 response, with IL-5 and IL-13 activating B cells and NK T cells." (PMID 40507438, 2025). "Anti-TNF agents play a crucial role in the management of severe ulcerative colitis." (PMID 41155452, 2025). "Relative studies found that in vivo administration of ferulic acid alleviated intestinal damage in ulcerative colitis (UC) rats and suppressed the expression of inflammatory factors TNF-α, IL-12, and IL-1β, indicating that ferulic acid possesses significant anti-inflammatory activity." (PMID 40428394, 2025). "Carrying the HLA-DQA1*05 allele doubles the risk of developing immunogenicity to anti-TNF therapy and is associated with an increased likelihood of not having a therapeutic response to ulcerative colitis." (PMID 41010030, 2025). "In addition, NCAPD3‐induced activation of IKK/NF‐κB pathway and secretion of proinflammatory cytokines TNF‐α/IL‐6 promote the development of ulcerative colitis." (PMID 39917394, 2025). "Proinflammatory TNFα/NFκB signaling is believed to play a cardinal role in ulcerative colitis." (PMID 40605975, 2025). "TNF-α is secreted by macrophages, as well as by other cells (T lymphocytes, B cells, dendritic cells, NK cells, mast cells, endothelial cells and fibroblasts), and its over-expression in ulcerative colitis is correlated with disease activity and severity." (PMID 41010030, 2025). "The results showed that cycloastragenol treatment improved the induced morphological changes, and in ulcerative colitis rats, this compound significantly reduced expression levels of SphK, MIP-1α, BAX, NF-κB, TNF-α, and active caspase-3, associated with BCL2 and miR-143 overexpression." (PMID 41304636, 2025).
ulcerative colitis (continued). "Through network pharmacology and molecular docking, we revealed HZ's intricate multi‐compound, multi‐target, and multi‐pathway intervention in promoting ulcerative colitis, specifically within Toll‐like receptor, NF‐kappa B, T cell receptor, and TNF signaling pathways." (PMID 41164267, 2025). "Additionally, podophyllotoxin significantly lowered the levels of inflammatory cytokines (TNF-α, IL-1β, IL-6) in the serum and colonic tissues of ulcerative colitis model mice and improved oxidative stress status." (PMID 40432443, 2025). "Studies indicate that they may be beneficial in treating ulcerative colitis (UC) by modulating intestinal immunity and reducing proinflammatory cytokines such as TNF-α and IL-1β while increasing anti-inflammatory factors like IL-10." (PMID 40077619, 2025). "For instance, cecropin A not only effectively reduced the levels of proinflammatory factors TNF-α, IL-6, and IL-1β in the colon tissues of mice with ulcerative colitis but also reduced the E. coli-induced expression of IL-6, IL-8, and TNF-α mRNAs in porcine intestinal epithelial cells (IPEC-J2)." (PMID 41099619, 2025). "To investigate the effects of DID on the expression of inflammatory factors and intestinal barrier protein in colonic tissues of mice with DSS-induced ulcerative colitis, we detected the expressions of IL-6, IL-1β and TNF-α in DSS-stimulated colon tissues via Western blot." (PMID 39452928, 2024). "Ulcerative colitis in rats increased the expression of TNF-α, MMP9 and IL-13." (PMID 38321559, 2024). "Moreover, according to previous research findings of our research group, GFP also decreased the expression of pro-inflammatory cytokines tumor necrosis factor (TNF)-α reduced colon injury in ulcerative colitis mice." (PMID 39063539, 2024). "Oral administration of CTZ (20 mg/kg) and LOR (10 mg/kg) for 7 days after induction of ulcerative colitis, showed a significant P>0.05 decrease in TNF-α (60.39±1.97 and 53.02±0.76 pg/mg protein, respectively) as compared to AA group (3.21 and 3.66 fold decrease, respectively)." (PMID 38645494, 2024). "Overall, the expression pattern and level of EFHD2 in the intestinal epithelium might be predictive of responsiveness to anti-TNF therapy of ulcerative colitis." (PMID 38346956, 2024). "As an ingredient in TCM with dual applications in both medicinal treatment and dietary consumption, D. lablab flowers have been reported to significantly suppress the expression of inflammatory cytokines such as IL-6, TNF-α, and IL-1β in a mice model of ulcerative colitis." (PMID 39202831, 2024). "Related to that, an increase in the main pro-inflammatory markers such as TNF-α and IL-6, together with an increase in the relative abundance of Alloprevotella, were detected in a mice model of ulcerative colitis, suggesting altogether the possible role of this genus in inflammatory status." (PMID 38999973, 2024). "Methods and Results: Our results indicated that didymin could alleviate the symptoms of ulcerative colitis, as it inhibited the expressions of interleukin-6 (IL-6), interleukin-1β (IL-1β) and tumor necrosis factor-α (TNF-α)." (PMID 39452928, 2024). "Pharmacological research shows that a 90% ethanol extract of D. lablab flowers can also significantly suppress the expression of inflammatory cytokines such as IL-6, TNF-α, and IL-1β in a mice model of ulcerative colitis and promote the recovery of intestinal epithelial tight junctions." (PMID 39202831, 2024). "Golimumab is another anti-TNFα mAb recently approved for the treatment of ulcerative colitis only." (PMID 37764213, 2023). "Inflammatory bowel disease: Jakinibs are the most recent therapeutic agents for managing chronic inflammatory bowel diseases such as ulcerative colitis and Crohn’s disease, exhibiting better pharmacokinetic and lack of immunogenicity compared to other biological counterparts (TNF inhibitors)." (PMID 37021053, 2023).